ITGA3 (integrin subunit alpha 3)
Diseases named in the same sentence as ITGA3 in open-access papers (continued):
Sharing a sentence is not in itself a finding about the gene and the disease.
tumor (continued). "The ITGA-3 and ITGB-5 gene expression levels in the tumor tissue as determined using RT-PCR were not considered significant when analyzed with regard to the different measures of tumor dissemination outcome, except for those related to TNM staging and cell differentiation degree." (PMID 24737953, 2014). "The moderate reduction of tumorigenesis in the K19 Itga3 KO mice, compared with the near complete absence of tumor formation in mice carrying a targeted deletion of Itga3 in the whole epidermis, suggests that HB SCs might be the cells-of-origin for some, but not all DMBA/TPA–initiated tumors." (PMID 32423907, 2020). "This is of lesser concern, as we observed non-efficient deletion of α3 also in the HBs of K14 Itga3 KO mice, that is, the model in which DMBA/TPA treatment resulted in near absence of tumor formation." (PMID 32423907, 2020). "Although CCN2 could be detected in all K19 Itga3 WT tumors analyzed, a small number of CCN2-positive cells (the mean CCN2-positive surface is 0.27% of total tumor area) together with their non-HB origin indicates that CCN2 does not play a major role in the late stages of tumor growth." (PMID 32423907, 2020).
cancer (99 papers, 2002 to 2026). A tumor composed of atypical neoplastic, often pleomorphic cells that invade other tissues. "ITGA3 overexpression has been associated with enhanced invasive and migratory capabilities in various cancer cell types." (PMID 40181838, 2025). "Further analysis of ligand-receptor pairs revealed that VTN-(ITGAV + ITGB5), SEMA4D-PLXNB2, GAS6-TYRO3, and FN1-(ITGA3 + ITGB1) were more prevalent in high-risk cancer cells." (PMID 41034991, 2025). "ITGA3 is an integrin located on the cell membrane that functions as a cell surface adhesion molecule, and its expression is associated with cancer metastasis." (PMID 37631983, 2023). "It was reported that ITGA3 can interact with extracellular matrix protein, and its expression is associated with cancer metastasis." (PMID 34938358, 2021). "miRNAs such as hsa-mir-196a-5p and hsa-mir-29a-5p regulate the expression of cell adhesion molecules, including CD44, ICAM1, and ITGA3, and may therefore be associated with cell migration and cancer metastasis." (PMID 41226241, 2025). "ITGA3 has been confirmed to be associated with poor prognosis in a variety of cancers." (PMID 34759953, 2021). "ITGA3 was found to be associated with lymphatic dissemination and local invasiveness in cancers." (PMID 30155352, 2018). "Since, our gene expression profiling demonstrated a number of deregulated genes (e.g., PIKFYVE, ZKSCAN1, CYR61, ITGA3) associated with the microtubule cytoskeleton, we assumed that secalonic acid’s effect on microtubules may be related to its ability to inhibit cancer cell migration." (PMID 32679716, 2020). "Meanwhile, ITGA3 expression in cancer tissues is investigated through several clinicopathological factors to find the between its level of gene and potential role in progressions." (PMID 40181838, 2025). "ITGA3 is a cell surface adhesion protein that interacts with extracellular matrix proteins and is involved in cancer metastasis." (PMID 40013338, 2025). "A mutually exclusive mutation pattern between ITGA3 and ITGA1/2 suggested their different roles in cancer development." (PMID 39436262, 2024). "The expression of ITGA3 has been identified as a key molecular marker of various cancers in many omics studies." (PMID 37828502, 2023). "ITGA3 is a cell surface adhesion protein that cooperates with ECM proteins which function in cancer metastasis." (PMID 35053843, 2022). "Integrin subunit alpha 3 (ITGA3) expression correlates with the development and prognosis of human cancers." (PMID 36561844, 2022). "ITGA3 has been reported to account for the differentiation and metastasis of many cancer types through extracellular matrix interactions, focal adhesion, and other molecular mechanisms." (PMID 35186475, 2022). "ITGA3 is a cell surface adhesion protein that interacts with extracellular matrix proteins, and its expression correlated with cancer metastasis." (PMID 34366863, 2021). "PrognoScan, GEPIA, Kaplan–Meier plotter and Easysurv were utilized to analyze the prognosis of ITGA3 in certain cancers." (PMID 34094951, 2021). "We subsequently used the PrognoScan database and GEPIA database to assess the relationship between ITGA3 expression and cancer patient outcomes." (PMID 34094951, 2021). "Through the analysis of the expression and prognosis of ITGA3 in a variety of cancers, we found that ITGA3 is differentially expressed in several cancers and has a certain impact on prognosis, making it an adverse prognostic factor." (PMID 34094951, 2021). "Oncomine, the Human Protein Atlas (HPA) and UALCAN were used to analyze the expression of ITGA3 in various cancers." (PMID 34094951, 2021). "We examined the expression differences of ITGA3 between cancers and their normal tissues using GEPIA and Oncomine databases to explore the expression pattern in multicancers." (PMID 35174063, 2021). "Cancer cells proliferations were significantly reduced in si-ITGA3-1 and si-TNC transfectants in comparison with that in mock-transfected FaDu cells." (PMID 28415821, 2017).
cancer (continued). "Among these genes, our previous studies demonstrated that ITGA3, ITGA6, and CAV2 were overexpressed in cancer tissues and associated with cancer cell migration and invasion." (PMID 28415821, 2017). "ITGA3 is a member of the integrin family of proteins, which function as a cell surface adhesion molecules and has a role in cancer invasion." (PMID 25047265, 2014). "Integrin A3 (ITGA3), a cell adhesion molecule of the integrin family, plays a number of essential roles in processes required for cancer progression, including proliferation, survival, invasion, and metastasis." (PMID 24223753, 2013). "Importantly, cancer-associated fibroblasts (CAFs) secrete laminin-332 (LAM332), which engages ITGA3 on PDAC cells to promote proliferation and invasion, drive homotypic CTC clustering, and suppress apoptosis, collectively sustaining CTCs' survival." (PMID 41881953, 2026). "We crossed a floxed Itga3 allele into the KPC:APC model to generate KPC:APC:α3flx/flx mice, in which tamoxifen treatment (see Section 2) causes the Cre-mediated deletion of α3 simultaneously with the activation of the cancer-causing genetic lesions." (PMID 39941740, 2025). "It was reported that ITGA3 is highly expressed in different cancer types." (PMID 34938358, 2021). "Moreover, pathway enrichment analysis using GSEA revealed that several cancer-related pathways were involved in ITGA3 high expression group, including MAPK pathway and ERBB pathway." (PMID 35174063, 2021). "Therefore, we compared gene expression for cancer-associated fibroblast (CAF) markers including MMP2, MMP9, MMP21, TGFA, CXCL12, ITGA3, FAPα, and IL32 in fibroblasts derived from normal skin and MF tumors." (PMID 33941102, 2021). "The overexpressed integrin α (ITGA) subfamily genes ITGA2 and ITGA3 are predicted to be involved in cancer-related pathways such as PI3K-Akt signaling pathway and FA interacting with ECM genes such as laminin (LAMB3, LAMA3, and LAMC2) and collagen (COL10A1, COL12A1)." (PMID 34262595, 2021). "Therefore, the study of the regulatory effect of ITGA3 on TC can improve the theoretical construction of ITGA3 as a cancer regulator." (PMID 34938358, 2021). "From this analysis, we noted that multiple elevated transcripts within the extracellular matrix organization GO term, particularly, CD44, osteopontin (SPP1), SPARC, and integrin A3 (ITGA3), have been widely studied in GBM and implicated with cancer invasion/metastasis and severity." (PMID 33843470, 2021). "Therefore, the increased invasive potential of ITGA3 KO HER2+ carcinoma cells strongly depends on the presence of the interstitial fluid flow and a collagen I-rich extracellular matrix." (PMID 31101121, 2019). "ITGA3 is widely expressed in normal organisms, but under the effects of oncogene induction, chromatin structure changes, high expression of growth factor and its receptor, ECM changes and other factors such as the enhanced transcription of integrins cause disordered expression that induces cancer." (PMID 34094951, 2021). "ITGA3 may promote proliferation or invasion in various types of cancer." (PMID 29764514, 2018). "The common genes that exhibited concordant expression trends in CRC and PDAC KRAS‐mutant cells compared with their corresponding KRAS‐WT cancer cell lines were MUC1, ITGA3, and PHLDA." (PMID 40013338, 2025). "ITGA6 functions as an HPV receptor and has been linked to therapy resistance in HNSCC, making it an especially intriguing target in HNSCC In the cancer genome atlas (TCGA) dataset of HNSCC patients, ITGA3, ITGA5, and ITGA6 all show prognostic resolution." (PMID 40287842, 2025).
cancer (continued). "Consistent with the findings in those cancer types, we found that ITGA3 was highly expressed in PTC tissue, and patients with high ITGA3 expression showed a significantly poorer DFS." (PMID 39218967, 2024). "Remarkably, some receptors (ERBB2, ITGA3, and ITGB6) were mainly expressed in cancer cells, and their putative ligands (NRG1 and FN1) were over-expressed in CAFs." (PMID 37879219, 2023). "The top 5 identified genes affecting survival negatively (p < 0.05) in at least 4/9 cancer types were LOXL2, ITGA3, ACTB, EFNB2 and ITGB1." (PMID 37206618, 2023). "Further CellChat analysis revealed that the signaling pathways between cancer cells and identified CAFs (NRG1-ERBB2/4 and FN1-CD44/ITGAV/ITGA3/ITGB6/ITGB8/ITGB1) were specifically enriched in CAde and CSCC, respectively." (PMID 37879219, 2023). "KEGG analysis indicated that ITGA3 is involved in the MAPK signaling pathway, and ERK1/2 and JNK, which are members of the MAPK family, can induce cancer cells to generate MMPs to degrade the ECM and invade." (PMID 34094951, 2021). "In summary, this study provided evidence for the downregulation of ITGA3 in BRCA, which differed from other types of cancers, due to promoter methylation." (PMID 34094951, 2021). "ICAM1, ITGA3 and MMP1 are involved in the remodeling of the extracellular matrix, and their expression is known to be aberrant in some cancers." (PMID 32899628, 2020). "Our recent studies identified the overexpression of ITGA3 in PDAC and showed that its expression enhanced cancer cell migration and invasiveness through the activation of several oncogenic pathways." (PMID 32977589, 2020). "RT‐qPCR was utilized to detect the expression pattern of MATN2, FOXE1, and ITGA3 in PTC and papa‐cancer tissues." (PMID 30941771, 2019). "GSEA revealed that the DE-ATGs in the high ITGA3, MAP1LC3A, and NRG1 expression groups in the TCGA GBM cohort were mainly enriched in KEGG pathways related to autophagy and cancer." (PMID 31844032, 2019). "The FOXE1 and ITGA3 were significantly raised to 2.5 and three times in PTC comparing to papa‐cancer tissues." (PMID 30941771, 2019). "Laminin-332 can interact with two types of integrins, ITGA6/ITGB4 (α6β4) and ITGA3/ITGB1 (α3β1), and activation of laminin-332-mediated integrin signalling enhances cancer cell development and metastasis." (PMID 29423074, 2018). "ITGA3 and ITGB1 form a specific type of integrin receptor (ITGA3/ITGB1), and dysregulation of ITGA3/ITGB1-mediated signaling enhances cancer cell aggressiveness in several types of cancer." (PMID 29988949, 2018). "Among 5 genes, we focused on ITGA3, ITGA6, and TNC genes because aberrant integrin-mediated signalling promoted cancer cell aggressiveness according to our previous studies." (PMID 28415821, 2017). "Our large cohort study using TCGA datasets indicated that the expression levels of ITGA3, ITGA6, and TNC were upregulated in cancer tissues." (PMID 28415821, 2017). "Knockdown assays using siRNAs showed that ITGA3, ITGA6 and TNC acted as cancer promoting genes in HNSCC cells." (PMID 28415821, 2017). "Cancer Pathway cDNA microarray analysis revealed that DACT1α down-regulated cell adhesion receptors from the integrin family including ITGA1, ITGA2, ITGA3 and ITGB3." (PMID 27833078, 2016). "Due to the established role of NRAS, ITGA3 and STAT5 in cancer progression and cell death/survival, we focused on them." (PMID 24400121, 2014). "The proteins ITGA3 and ITGB1 were abundant in cancer cell exosomes and in the secretome of metastatic cell lines." (PMID 24371517, 2013). "In addition, ITGA3, ITGA5, and ITGA6 show activating effects on the KEGG pathway in cancer, which is consistent with previous analysis results." (PMID 41602372, 2026). "Furthermore, KEGG pathway analysis identified the PI3K-AKT signalling (p = 0.002) and focal adhesion (p = 0.003) pathways in cancer (p = 0.001), and ECM-receptor interaction (p = 7.95E-8) to be connected with ITGA3." (PMID 40138447, 2025).
cancer (continued). "Co-expressed genes (PXN, ITGA3, TES, and MET) were identified and analyzed by FunRich with CAV1 and CAV2, revealing a significant correlation with focal adhesion (p < 0.001), which has a vital influence on cancer progression." (PMID 36830672, 2023). "Furthermore, miR-150 regulates cancer cell migration by affecting multiple effectors including matrix metalloproteinases (MMP14 and MMP13), cell adhesion molecules (ITGA3, ITGA6), transcription factors (MYB), and epigenetics factors (HMGA2 and EZH2)." (PMID 37924077, 2023). "The genes ITGA3, HSPA8, CTSD, ATG12, CLN3, ATG7, and MAP1LC3C negatively influenced patient survival, whereas WIPI1 may protect the patients from cancer-related death." (PMID 35186475, 2022). "Also, ITGA2, ITGA3 and ITGA6 are integrin coding genes that participate in cell adhesion, proliferation, and differentiation and are known to have anti-cancer properties in LC." (PMID 35600397, 2022). "Another very prominent pathway in cancer is ERK/MAPK signaling (p = 3.47 × 10−2; ESR1, FYN, ITGA3, PIK3R3, PLA2G4A, PLA2G5, RPS6KA5), which is the core of the signaling network involved in regulating cell growth, development, and division and a target of many cancer therapeutics." (PMID 35106465, 2022). "Furthermore, we found that some ITGs such as ITGA3, ITGA6 ITGA11, ITGB4, ITGB6, etc. were frequently upregulated in human cancers, whereas ITGs including ITGA1, ITGA7, ITGA8, ITGA9 and ITGB3, etc. were usually downregulated." (PMID 34222028, 2021). "the down-regulation of ITGA3 reduces the phosphorylation of AKT, extracellular signal-regulated kinases 1 and 2 (ERK1/2), and focal adhesion kinase (FAK) in SAS cells and significantly inhibited migration of cancer cells and invasion of HNSCC cells." (PMID 34631779, 2021). "Moreover, overexpression of miR-124-3p inhibited ITGA3/ITGB1-mediated oncogenic signaling, and attenuated cancer cell migration and invasive abilities." (PMID 34199886, 2021). "Lastly, no changes in ITGA3 expression were observed in any of the cells, though it has been reported to be over-expressed in many cancers." (PMID 32899628, 2020). "In contrast, all three HER2-driven carcinoma cell lines exhibited very low invasive potential, with no obvious differences between the ITGA3 KO and WT cells." (PMID 31101121, 2019). "However, as a classical cell surface adhesion molecule, we found ITGA3 correlated negatively with the migration and invasion of ICC cell lines, which differs from other malignant tumors." (PMID 29511671, 2018). "ITGA3 and ITGA6 were strongly expressed in several cancer tissues." (PMID 28415821, 2017). "In line with miR-223 function are the evidences that integrins, in particular ITGA3 and ITGB1, are key mediators of the outside-in and inside-out signalling in cancer and their depletion leads to decreased migratory abilities and inhibition of metastasis formation." (PMID 24400121, 2014). "The eight IA genes we identified are associated with cellular cytoskeleton, cell invasion and oncogenetic signaling, including the well-known cancer driver EGFR, and FAK-Src signaling (ITGA3, MYLK); ITGA3 (integrin, alpha 3) mediates cell survival and invasion through FAK-Src signaling." (PMID 23590835, 2013). "ITGA3 expression was also not significantly related to age, which indicates there may be no age effect for ITGA3 in cancer tissues." (PMID 40181838, 2025). "Notably, none of these pairs have been directly associated with TGFβ signaling or EMT, although many of the identified ligands (e.g., LAMC2) or receptors (e.g., CD151, COL17A1, ITGA2, ITGA3, ITGA6, ITGB1, and ITGB4) occur frequently in the context of EMT and/or cancer." (PMID 36755019, 2023). "Analysis of the expression of ITGA3 in pan-cancer and its normal tissues based on TCGA datasets using GEPIA web-based tool revealed that 11 cancers displayed significantly higher ITGA3 expression and 5 cancers displayed lower ITGA3 expression compared to their normal tissues." (PMID 35174063, 2021).
cancer (continued). "Furthermore, we found that the membrane proteins CDH2, EGFR, ITGA3, ITGA5, ITGB1, and CALR may have significant effect on cancer prognosis and outcomes, which were further validated in vitro." (PMID 33005184, 2020). "Moreover, integrin α3 (ITGA3) and β1 (ITGB1), heterodimeric transmembrane receptors, were also overexpressed in naïve PCa clinical specimens, and integrin‐mediated oncogenic signaling enhanced cancer cell aggressiveness." (PMID 29608247, 2018).
infection (2 papers, 2019 to 2025). The state of being infected such as from the introduction of a foreign agent such as serum, vaccine, antigenic substance or organism. "Although the changes in ITGA3 and CTNNA1 were not large enough to be deemed significant in this dataset, their slight elevation might contribute to subtle modifications in cell-cell contacts during infection." (PMID 40630640, 2025).
infectious disease (1 paper, 2025). A disorder directly resulting from the presence and activity of a microbial, viral, or parasitic agent in humans. "This study not only establishes physiologically relevant immuno‐lung organoid models for modeling macrophage‐mediated tissue damage, but also identifies a previous unrecognized role of the THBS1‐(ITGA3+ITGB1) pathway in driving lung cell senescence during infectious disease." (PMID 40712141, 2025).
kidney disease (1 paper, 2025). "Dysregulation of ITGA3 can lead to podocyte dysfunction, proteinuria, and kidney disease." (PMID 41368354, 2025).
ITGA3 also shares sentences with these, for which no sentence is quoted: oral squamous cell carcinoma (3 papers); small cell lung carcinoma (3); tongue squamous cell carcinoma (3); adenocarcinoma (2); endometrial cancer (2); fibrosis (2); intrahepatic cholangiocarcinoma (2); metastatic prostate carcinoma (2); Sepsis (2); viral infection (2); acute respiratory distress syndrome (1); basal cell carcinoma (1); benign tumors (1); bladder tumor (1); breast invasive carcinoma (1); breast tumor (1); cholangiocarcinoma (1); chronic myeloid leukemia (1); Cirrhosis (1); colorectal adenocarcinoma (1); COVID-19 (1); endocrine cancer (1); eye cancer (1); focal segmental glomerulosclerosis (1); genetic disorders (1); hydronephrosis (1); idiopathic pulmonary fibrosis (1); Insulin resistance (1); kidney cancer (1); leishmaniasis (1).
A further 23 diseases each share a sentence with ITGA3 in 1 paper.